SERPINA13P (serpin family A member 13, pseudogene )
Synonyms: SERPINA13; UNQ6121
Gene: Long non-coding RNA gene on chromosome 14 (94,640,725 to 94,646,994, forward strand). Ensembl gene ENSG00000290676.
Diseases named in the same sentence as SERPINA13P in open-access papers:
SERPINA13P is named in the same sentence as 18 diseases in open-access papers, as found by Europe PMC text mining. Sharing a sentence is not in itself a finding about the gene and the disease.
SERPINA13P shares sentences with these, for which no sentence is quoted: alpha 1-antitrypsin deficiency (3 papers); infection (3); tumor (3); benign ovarian tumours (1); cancer (1); cholangiocarcinoma (1); chronic obstructive pulmonary disease (1); Ehlers-Danlos syndrome (1); epilepsy (1); glioma (1); hereditary angioedema (1); Hypertension (1); liver disease (1); male infertility (1); neurological disease (1); otitis media (1); ovarian carcinoma (1); rheumatoid arthritis (1).